CSF1 (colony stimulating factor 1)
Diseases named in the same sentence as CSF1 in open-access papers (continued):
Sharing a sentence is not in itself a finding about the gene and the disease.
leiomyosarcoma (6 papers, 2014 to 2023). An uncommon, aggressive malignant smooth muscle neoplasm, usually occurring in post-menopausal women. "In leiomyosarcomas and osteosarcomas, CSF-1R was found to be highly expressed by TAMs, and, in leiomyosarcomas, expression of CSF-1 and related proteins have also been associated with worse clinical outcomes." (PMID 34440251, 2021). "Previous studies showed that CSF1 exerted important roles in promoting tumor angiogenesis in leiomyosarcoma and Lewis lung carcinoma cells via VEGF induction." (PMID 24614175, 2014). "Moreover, they analyzed CSF1 mRNA ISH in various types of soft tissue tumor including leiomyosarcoma and undifferentiated pleomorphic sarcoma and CSF1 mRNA expression pattern was similar to the punctate pattern seen in TSGCTs." (PMID 36320082, 2022). "Moreover, we performed CSF1 IHC in undifferentiated pleomorphic sarcoma, leiomyosarcoma, and myxofibrosarcoma (MFS) as these tumors may contain osteoclast-like giant cells." (PMID 36320082, 2022). "All cases of undifferentiated pleomorphic sarcoma, leiomyosarcoma, and myxofibrosarcoma were negative for CSF1." (PMID 36320082, 2022). "Notably, in leiomyosarcoma, TJP1 knockdown led to the activation of multiple signaling pathways, including the NF-κB pathway and growth factor receptor signaling, resulting in enhanced tumor growth because of CSF1 and CTLA4 expression." (PMID 37790849, 2023). "We performed CSF1 IHC in 110 cases including 44 LTSGCTs, 20 DTSGCTs, 1 malignant TSGCT (MTSGCT), 10 giant cell tumors of bone, 2 giant cell reparative granulomas, 3 aneurysmal bone cysts, 10 undifferentiated pleomorphic sarcomas, 10 leiomyosarcomas, and 10 myxofibrosarcomas." (PMID 36320082, 2022). "We revealed characteristic CSF1 expression on IHC in only cases of TSGCT and not in GCRTs and GCRT-like lesions such as giant cell tumor of bone, aneurysmal bone cyst, giant cell reparative granuloma, undifferentiated pleomorphic sarcoma, leiomyosarcoma, and myxofibrosarcoma." (PMID 36320082, 2022).
multiple sclerosis (6 papers, 2016 to 2025). A progressive autoimmune disorder affecting the central nervous system resulting in demyelination. "In an animal model of multiple sclerosis, treatment with anti-CSF-1 was shown to selectively deplete myeloid cells in the inflammatory regions of the CNS." (PMID 38737586, 2024).
Paget disease (6 papers, 2014 to 2024). A malignant neoplasm composed of large cells with large nuclei, prominent nucleoli, and abundant pale cytoplasm (Paget cells). "It is known that M-CSF plays a key role in osteoclast differentiation and that genetic variations upstream of the CSF1 gene which encodes M-CSF predispose to Paget’s disease." (PMID 39349622, 2024). "In humans, genetic susceptibility to disordered bone turnover in Paget disease has been linked to variation at the Csf1 locus." (PMID 30249809, 2018). "Variation in the vicinity of an upstream enhancer at the CSF1 locus is very strongly linked to Paget’s disease, and there is some evidence of association with UC at the same interval." (PMID 28263993, 2017). "In humans, variation at the CSF1 locus has been implicated in bone loss in Paget's disease." (PMID 24652541, 2014).
pigmented villonodular synovitis (6 papers, 2015 to 2024). Outgrowths of synovial membrane composed of villi and fibrous nodules characterized histologically by hemosiderin- and lipid-containing macrophages and multinucleated giant cells. "Analogous to these observations, interfering with signaling from CSF1 produced by the tumor cells in pigmented villonodular synovitis can markedly decrease macrophage infiltration and have striking beneficial effects." (PMID 30999901, 2019). "dt-GCT of the soft tissue (alternatively known as pigmented villonodular synovitis [PVNS]) is an orphan disease characterized by overexpression of CSF1 and is usually caused by chromosomal translocations involving chromosome 1p13 where the CSF1 gene is located." (PMID 28716061, 2017).
prion disease (6 papers, 2009 to 2020). A transmissible disease that is caused by a protein that is able to induce abnormal folding of normal cellular proteins, leading to characteristic spongiform brain changes, which are associated with neuronal loss without an inflammatory response. "It is well described that uPA is robustly upregulated by macrophage CSF-1, and we have found evidence for increased transcription of CSF-1 in the ME7 prion disease model (unpublished observations)." (PMID 19459212, 2009). "The expression of CSF1 and its receptor CSF1R show similar patterns, appearing upregulated in prion disease, with the CCR2−/− background having a less pronounced effect." (PMID 24648328, 2014). "IL-34 levels were around 300 times higher in the naïve brain than CSF-1 levels, but not changed in the context of prion disease or after IL-34 antibody treatment." (PMID 33162994, 2020). "It is possible that in the genetically modified mice with a constitutive loss of function of IL-34, CSF-1 compensates for the absence of IL-34 and drives proliferation through CSF1R to expand the microglial population in prion disease." (PMID 33162994, 2020).
prostate tumor (6 papers, 2019 to 2025). "CSF-1 is reportedly increased in irradiated prostate tumors, which enhances tumor-infiltrating TAMs and MDSCs that can limit the efficacy of radiotherapy in prostate tumor murine model." (PMID 32824865, 2020).
sarcoma (6 papers, 2018 to 2025). A usually aggressive malignant neoplasm of the soft tissue or bone. "OS cells expressed CSF1, which has been shown to be associated with protumor activity of tumor-associated macrophages in multiple sarcomas, including OS, and is a regulator of proliferation and survival." (PMID 40647416, 2025). "KP sarcoma cell lines also produced CSF-1, and much more robustly than did B16 cells." (PMID 29757143, 2018). "Thus, antibody blockade of the CSF-1/CSF-1R axis suppresses RAE-1δ expression by TAMs in B16 S.C. tumors and autochthonous KP sarcomas." (PMID 29757143, 2018).
thyroid cancer (6 papers, 2013 to 2025). "It has been demonstrated that conditional activation of oncogenic BRAF in mouse results in the induction of thyroid cancers with increased CCL2 and CSF1 expression, associated with the recruitment of tumour-associated macrophages (TAMs)." (PMID 34299284, 2021). "We tested the mRNA levels of six more genes, including three with different abundance in antibody array between FTC and FA, two previously reported TAMs recruiters (CCL2 and CCL7), and CSF-1 which was reported as TAMs recruiters in thyroid cancers." (PMID 26875556, 2016). "Mice study showed that CSF1/CSF1R mediated TAMs recruitment in papillary thyroid cancer (PTC) and targeting CSF1/CSF1R impaired BRAF-induced thyroid cancer progression." (PMID 26875556, 2016). "In addition, in a murine model of thyroid cancer, it has been demonstrated that targeting TAMs trough inhibition of CSF-1/CSF-1R impairs BRAFV600E-induced thyroid cancer progression." (PMID 34681084, 2021). "In thyroid cancer, the expression levels of SPP1 and CSF1 are significantly up-regulated, while CSF1R inhibitor can reduce their expression, thereby inhibiting tumor cell proliferation." (PMID 37097499, 2023). "Mice were treated with doxycycline for one week to develop thyroid cancer, and the expression levels of CCL2, CSF-1, LGALS3BP, INPP5D and CCL7, together with that of the chemokine receptors CCR2 and CSF1R, were measured in cancer specimens by quantitative RT-PCR." (PMID 34299284, 2021). "Given that FOXE1 expression induces both CCL2 and CSF1, together with other chemoattractants, in thyroid cells in vitro, we asked if FOXE1 could modulate the oncogenic induction of chemokines and hence the infiltration of thyroid cancer by TAMs in vivo." (PMID 34299284, 2021).
type 2 diabetes (6 papers, 2009 to 2024). "DAVID was used to identify the functions of these genes, and TIRAP, TNFRSF1A, CASP1, CSF1, and ITGAM were associated with type 2 diabetes." (PMID 39194753, 2024).
dementia (5 papers, 2015 to 2024). Loss of intellectual abilities interfering with an individual's social and occupational functions. "Furthermore, it has been suggested that colony stimulating factor 1 (CSF1) is involved in the dementia prevention mechanism by oral administration of LPS." (PMID 36969154, 2023).
Insulin resistance (5 papers, 2020 to 2023). Increased resistance towards insulin, that is, diminished effectiveness of insulin in reducing blood glucose levels. "We focused on the metabolic effects of CSF1 inhibition since tissue macrophages play a crucial role in insulin resistance and beta cell dysfunction." (PMID 37792013, 2023). "Insulin resistance-associated factors, such as IGF1 and IGFALS, and inflammation-related factors, such as CSF1 and TGFβ2, were all highly enriched in the MetS group." (PMID 32133283, 2020).
invasive breast carcinoma (5 papers, 2011 to 2024). A carcinoma that infiltrates the breast parenchyma. "It is found that CSF‐1‐positive cancer cells colocalize with abundant CSF‐1R‐positive TAMs in invasive breast cancer, and the CSF‐1/CSF‐1R axis is significantly correlated with a higher grade, basal‐like phenotype, and lymph node metastasis." (PMID 33463063, 2021). "In an invasive breast cancer mouse model, macrophages have been implicated in assisting tumor cell motility by participating in an epidermal growth factor- (EGF-) CSF-1 paracrine loop where tumor cells secrete CSF-1 and macrophages contain the corresponding receptor and vice versa." (PMID 25054153, 2014).
ischemia (5 papers, 2020 to 2024). A hypoperfusion of the BLOOD through an organ or tissue caused by a PATHOLOGIC CONSTRICTION or obstruction of its BLOOD VESSELS, or an absence of BLOOD CIRCULATION. "Based on this, we conclude that CSF-1 mediates the adaptation of monocytes and macrophages to ischemia." (PMID 37691936, 2023). "Colony stimulating factor 1 (CSF1), binding to CSF1 receptor (CSF1R), has been shown to reduce neuronal loss after hypoxic-ischemia- (HI-) induced brain injury." (PMID 33101590, 2020).
mesothelioma (5 papers, 2014 to 2021). A usually malignant and aggressive neoplasm of the mesothelium which is often associated with exposure to asbestos. "In order to obtain insights on the clinical impact of the CSF1R/CSF1 axis in mesothelioma, we investigated potential links between tumor CSF1R expression, tumor macrophages and clinical outcomes using the TCGA RNAseq data of mesothelioma patients." (PMID 34067348, 2021). "This study aimed to define the impact of CSF1/CSF1R axis blockade in experimental mesothelioma progression and its potential to enhance the efficacy of immune checkpoint therapy." (PMID 34067348, 2021). "In the clinic, abundant macrophage infiltration, CSF1 pleural levels and PDL1 expression have been linked to poor prognosis of mesothelioma patients." (PMID 34067348, 2021). "We hypothesized that CSF1/CSF1R inhibition would limit mesothelioma progression by targeting immunosuppressive macrophages." (PMID 34067348, 2021). "Colony-Stimulating Factor 1 (CSF1)/Colony-Stimulating Factor Receptor (CSF1R) signaling plays important role in the recruitment of monocytes into mesothelioma tumors, their differentiation into M2-like macrophages, impaired CD8 T cell cytotoxicity and chemoresistance." (PMID 34067348, 2021). "We hypothesized that CSF1/CSF1R inhibition would halt mesothelioma growth by targeting immunosuppressive M2 macrophages and unleashing efficient T cell responses." (PMID 34067348, 2021). "Therefore, we investigated the involvement of the CSF-1R/CSF-1/IL-34 system in mediating the resistance of the mesothelioma cells to pemetrexed." (PMID 24722292, 2014). "To obtain a suitable experimental system to study the CSF-1R function in mesothelioma cells, we analyzed the expression of CSF-1R and its ligands CSF-1 and IL-34 in a panel of mesothelioma cell lines and an untransformed mesothelial cell line immortalized by h-TERT (LP9)." (PMID 24722292, 2014). "Colony-Stimulating Factor 1 (CSF1)/Colony-Stimulating Factor Receptor 1 (CSF1R) signaling orchestrates tumor-associated macrophage (TAM) recruitment and polarization towards a pro-tumor M2 phenotype, the dominant phenotype of TAMs infiltrating mesothelioma tumors." (PMID 34067348, 2021). "Next, ELISA assay revealed that 7/7 mesothelioma cell lines secreted IL-34 and 6/7 MPM cell lines secreted CSF-1, with the levels of IL-34 being generally higher than those of CSF-1." (PMID 24722292, 2014). "The increased pool of macrophage progenitors with aging may have consequences for CSF-1 producing cancers, including AE17 murine mesothelioma." (PMID 30459812, 2018). "Although both mesothelioma cell lines were found to secrete CSF1 and express CSF1R (by a small percentage of the cells), neither CSF1 nor CSF1Ri affected their survival in vitro." (PMID 34067348, 2021).
non-small cell lung carcinoma (5 papers, 2014 to 2025). A group of at least three distinct histological types of lung cancer, including non-small cell squamous cell carcinoma, adenocarcinoma, and large cell carcinoma. "It has been reported that macrophage colony-stimulating factors (M-CSF, CSF-1) can significantly promote tumor tissue growth in tumor models constructed from non-small cell lung cancer cell line." (PMID 36969873, 2023).
ovarian tumors (5 papers, 2014 to 2022). "The prognosis of breast or ovarian tumour could be affected by the stability of macrophage colony-stimulating factor 1, which was regulated through m1A demethylation." (PMID 36147503, 2022). "Ovarian tumor cells, mainly via CSF-1, induce TAMs to exert pro-tumoral activity." (PMID 32456078, 2020). "Moreover, both the p-BRD4 and CSF1 levels correlated significantly with the numbers of TAMs in human ovarian tumors (r = 0.6976 and r = 0.4213, respectively)." (PMID 32286255, 2020). "M-CSF, known as a colony stimulating factor 1 (CSF-1), is also a potent chemoattractant for monocytes, which in turn, can produce factors that stimulate proliferation of ovarian tumor cells including interleukin-1 (IL-1), interleukin-6 (IL-6) and tumor necrosis factor (TNF)." (PMID 25935153, 2015). "Ovarian tumors recruit circulating monocytes and induce differentiation into TAMs via expression of factors such as CCL2, also known as monocyte chemotactic protein-1 (MCP-1), and macrophage colony stimulating factor-1 (M-CSF or CSF-1)." (PMID 24936477, 2014).
Splenomegaly (5 papers, 2015 to 2021). Abnormal increased size of the spleen. "CSF1 treatment in mice was reported to cause splenomegaly and to promote liver and kidney growth or repair." (PMID 25857347, 2015). "Previously, excessive human recombinant CSF-1 was given to mice and was found to lead to similar splenomegaly and excessive monocyte differentiation phenotypes reported here in this study." (PMID 34550965, 2021). "Despite splenomegaly the number of Ki67+ proliferating cells present in spleen was substantially reduced at day 7 post-CSF1-Fc treatment." (PMID 33402221, 2021).
ZIKV infection (5 papers, 2019 to 2023). "After analyzing the healthy brain organoid independently of tumor cell co-culture, we verified that the ZIKV infection induced the overexpression of the Csf1 and the BMPs family, genes important for normal neural development, only in tumor-free organoids." (PMID 34696533, 2021).
Anxiety (4 papers, 2022 to 2024). Intense feelings of nervousness, tension, or panic often arise in response to interpersonal stresses. "Notably, CSF1 is upregulated by mPFC neurons following stress leading to microglia-mediated spine pruning underlying anxiety- and depressive-like behaviors." (PMID 35668157, 2022). "We found that CSF1 overexpression significantly increased the latency to feed in an open arena in the novelty-suppressed feeding test, suggesting an increase in anxiety-like behavior." (PMID 35668157, 2022). "We found that mPFCCRF1+ ablation and CSF1 overexpression studies both altered behavior in the novelty-suppressed feeding test, suggesting this population regulates anxiety-like behavior in both male and female mice." (PMID 35668157, 2022). "Indeed, stress-induced increases in mPFC CSF1 expression leads to microglia-mediated synaptic pruning, and CSF1 knockdown was sufficient to reverse stress-induced anxiety and depressive behaviors." (PMID 35668157, 2022). "Indeed, we demonstrated that withdrawal-induced molecular adaptations in CSF1 expression in mPFCCRF1+ neurons are sufficient to heighten anxiety and recapitulate the reduced postsynaptic glutamate transmission seen in this population in withdrawal." (PMID 35668157, 2022). "Indeed, mPFCCRF1+ CSF1 overexpression increases anxiety-like behavior, highlighting CSF1 overexpression as a critical neuroadaptation that may contribute to negative affect in withdrawal." (PMID 35668157, 2022). "Moreover, we identified a neuroimmune mechanism, via colony-stimulating factor 1 (CSF1), underlying the observed mPFCCRF1+ adaptations in glutamate transmission and sufficient to induce aberrant anxiety-like behavior, which may increase relapse susceptibility." (PMID 35668157, 2022). "Interestingly, a study reported increased Csf1 mRNA in isolated microglia from mice submitted to chronic unpredictable stress and further, mice bearing a knockdown of neuron-derived Csf1 failed to develop chronic unpredictable stress–induced anxiety- and depressive-like behaviors." (PMID 36549907, 2023).
B-cell lymphomas (4 papers, 2020 to 2023). "Epithelial cells expressing VAV1 secrete CSF-1 and possibly other cytokines that influence the development of B-cell lymphoma." (PMID 37174676, 2023). "As demonstrated by IHC of lung, liver and pancreas sections with anti-Vav1, anti-CSF-1R and anti-CSF-1 Abs, while CSF-1R is expressed in cells within the B-cell lymphoma, the ligand is expressed in the epithelial tissue where transgenic Vav1 is found." (PMID 35326399, 2022). "Taken together, our results suggest a potential cross-talk between epithelial cells expressing Vav1, that secrete CSF-1, and the lymphocytes that express CSF-1R, thus leading to the generation of B-cell lymphomas." (PMID 35326399, 2022). "It was found that there is potential crosstalk between epithelial cells of VAV1 (which secrete CSF-1) and lymphocytes expressing CSF-1R, which leads to B-cell lymphoma." (PMID 35957889, 2022). "Owing to its impact on the development of myeloid cells, CSF-1 is among important soluble factors in the B cell lymphoma microenvironment." (PMID 32899476, 2020). "CSF-1 in turn activates the CSF-1R on B-cells and leads to enhancement of ERK phosphorylation and cell propagation, leading eventually to the development of B-cell lymphoma." (PMID 35326399, 2022).
breast adenocarcinoma (4 papers, 2012 to 2019). "The efficacy of paclitaxel in a mammary adenocarcinoma mouse model was enhanced by the blockade of CSF-1R/CSF-1, with paclitaxel upregulating the production of CSF-1." (PMID 31547627, 2019). "Seminal studies showed that ablating macrophages genetically by deleting the colony-stimulating factor 1 gene, Csf1, in a transgenic mouse model of breast adenocarcinoma delays tumor development and the angiogenic switch to prevent metastasis." (PMID 29220404, 2017).